NOTCH2 (notch receptor 2)
Diseases named in the same sentence as NOTCH2 in open-access papers (continued):
Sharing a sentence is not in itself a finding about the gene and the disease.
tumor (continued). "High levels of Notch1 correlates to higher numbers of tumor-associated macrophages (TAMs) in head and neck cancer and NOTCH1 and NOTCH2 induce a TAM-anti-inflammatory phenotype via JAG1." (PMID 32796631, 2020). "In order to identify the effect of DAPT on tumor progression by Notch2/DLL3 signaling pathway, Notch2/DLL pathways were detected by Western-blot." (PMID 31508369, 2019). "Our investigations indicate that NOTCH2 functions as a tumor suppressor by attenuating the TRAF6/AKT signaling cascade in NPC." (PMID 31699119, 2019). "The higher relevance of Notch1 than of Notch2 to the tumor-stroma-inflammation networks in TNBC was corroborated by similar findings that were obtained with NOTCH1 vs. NOTCH2 co-expression analyses performed with IL-1β." (PMID 31105691, 2019). "MTS experiment showed the cell viability was reduced to 74 ± 5.9, 61 ± 5.3, and 46.4 ± 4.6% in GH3 cells, and 94.5 ± 8.2, 88 ± 8.1, and 76 ± 7.4% in primary tumor cells after 24, 48, and 72 h knockdown of Notch2." (PMID 31508369, 2019). "Altogether, the results point to a functional axis of DLL4/DLL1 and Notch1/Notch2 as an essential element in DC-T-cell interactions needed for the induction of effector T-cell differentiation and eliciting T-cell-mediated anti-tumor immunity." (PMID 30940183, 2019). "Notch1 and Notch2 have been identified as key Notch receptors for eliciting T-cell effector function, including anti-tumor responses." (PMID 30940183, 2019). "Both Notch1 and Notch2 have been identified as key players in anti-tumor T-cell immunity including induction of tumor-specific cytotoxic T lymphocytes (CTL) and memory T-cells." (PMID 30940183, 2019). "Accordingly, immunofluorescence for Notch2 in histological sections of mouse tibias bearing MDA-MB-231 tumours revealed only a small percentage of MDAGFP cells to be Notch2HIGH." (PMID 31239543, 2019). "miR-107 functions as a tumor suppressor by reducing the expression of NOTCH2, CD133, nestin and Matrix Metallopeptidase 12 (MMP-12) in GSCs, impairing stem cell proliferation and invasion." (PMID 31450858, 2019). "Several proteins already known to promote tumor metastasis (NOTCH2, NCS1, NUSAP1, CD151), were increased more than 10-fold under hypoxic conditions, further demonstrating the potent effects of oxygen restriction on cancer cell biology." (PMID 31666928, 2019). "Notch2 is a target of another tumor-suppressive miRNA, miR-181c, which reduces cell proliferation, cell invasion, and self-renewal capacities through Notch2 downregulation." (PMID 30832246, 2019). "Notch-1 was negatively while Notch-2 was positively correlated with prognosis and therefore they play a completely different role in tumor formation and development." (PMID 31198409, 2019). "miR-34a and miR-34a-5p function as tumor-suppressive miRNAs, inhibiting cell proliferation, cell-cycle progression, and cell invasion by targeting Notch1, Notch2, c-Met, CDK6, and EGFR." (PMID 30832246, 2019). "Here we describe a signalling pathway underlying the mutual activation of BMSCs and tumour cells, which depends on the CLL-mediated activation of Notch2 in stromal cells, and the reciprocal activation of the canonical Wnt pathway in CLL cells." (PMID 30242258, 2018). "Proliferation of tumor cells was significantly reduced following Notch2 depletion, as indicated by Ki67 index." (PMID 29545603, 2018). "Intriguingly, CD8+ T cell-specific Notch2 deletion impairs antitumor immunity, whereas the stimulation of the Notch pathway can increase tumor suppression." (PMID 29441071, 2018). "It was found that the Notch2 vector attenuated the miR-1 inhibitory effect of miR-1 mimics on Notch2 protein in tumor cells." (PMID 29581534, 2018). "On the other hand CD8+ cytotoxic T cells, which have been shown to have anti-tumor function, require Notch to become activated, and Notch2 has been shown to be required for the anti-tumor effect of cytotoxic T lymphocytes." (PMID 30515368, 2018).
tumor (continued). "We show that tumour cells specifically induce Notch2 activity in mesenchymal stromal cells (MSCs) required for the transcription of the complement factor C1q." (PMID 30242258, 2018). "We then analyzed Notch2 expression in relationship to Sox9 in a human TCGA dataset containing 59 non-tumor livers and 36 human ICC samples." (PMID 29545603, 2018). "Notch2 activation in the microenvironment is a pre-requisite for the activation of canonical Wnt signalling in tumour cells." (PMID 30242258, 2018). "Immunostaining of Notch2 protein expression showed that tumour tissues had stronger Notch2 staining than did adjacent tissues." (PMID 30470250, 2018). "We observed ectopic expression of Dll4, Notch2 and 4 and Hes5 in the small intestine tumor epithelium." (PMID 28086833, 2017). "In a mouse model of lung cancer, Notch1 promotes tumor initiation and progression, whereas Notch2 has tumor suppressor functions." (PMID 29177029, 2017). "By combining the three tumors with NOTCH2 locus amplification and a tumor with NOTCH3 locus amplifications, seven tumors with an activated NOTCH pathway were identified out of 84 tumors." (PMID 28636652, 2017). "It has been shown that treatment of patient-derived xenograft tumors with anti-Notch-2 antibodies inhibits tumor growth and reduces the tumor-initiating cell frequency, suggesting the role played by Notch-2 in regulating CSC properties." (PMID 28270211, 2017). "Despite the structural similarity, NOTCH1 exerts tumor suppressive whereas NOTCH2 exerts oncogenic actions via different downstream signaling targets in other malignancies." (PMID 29242529, 2017). "In conclusion, NOTCH2 appears to be a key target of gliotoxin in human neoplasias and gliotoxin deserves further evaluation as a potential therapeutic agent in cancer management." (PMID 28736522, 2017). "miR-326 is a recognized tumor-suppressing miRNA, in fact among its targets there are Gli2, Smo, Notch1, Notch2 and Nob1." (PMID 28716052, 2017). "In order to further determine the tumor suppressive effect of Notch2, GC cells were transiently transfected with Notch2 coding sequence prior to ACGs treatment." (PMID 28416750, 2017). "The Notch 2/3 neutralizing antibody tarextumab inhibits tumor growth in mice not only in a variety of epithelial tumors but also in SCLC xenograft tumors." (PMID 27148486, 2016). "In contrast with the role of Notch1 in promoting tumor initiation and progression, Notch2 shows a tumor suppressive activity by mediating cell differentiation in lung carcinogenesis." (PMID 27847554, 2016). "C8orf4, which attenuated the self-renewal capacity of liver CSCs and tumor propagation, negatively regulated self-renewal of CSCs through suppression of NOTCH2 signaling." (PMID 27938406, 2016). "Of note, we observed that fractionated radiation increased the secretion of IL-6 in the tumor microenvironment through the activation of the JAK/STAT3/Notch2 signaling pathway as shown in a schematic model." (PMID 27462787, 2016). "In glioma, miR-34 was shown to inhibit tumor growth in vivo by down-regulating Notch1 and Notch2 expression." (PMID 26713603, 2016). "Notch2 has been described as a tumor suppressor in breast cancer cell lines, while Notch1, 3, and 4 are uniformly oncogenic in the breast." (PMID 27148486, 2016). "Other report shows that Notch2 is predominantly expressed in pancreatic intraepithelial neoplasia injuries and regulate the c-Myc signaling during tumor development." (PMID 27855169, 2016).
tumor (continued). "In these mice, Notch1 ablation resulted in decreased levels of the Notch target gene expression and of pERK1/2, resulting in reduced tumor formation, while Notch2 ablation showed an increase in HES1 expression and resulted in increased carcinogenesis." (PMID 26713603, 2016). "In a recent study, we demonstrated the prognostic relevance of NOTCH2 gene expression in residual tumor cells after chemotherapy of neoadjuvantly treated GC patients." (PMID 25954607, 2015). "C8orf4 is located in the cytoplasm of HCC tumour cells and associates with the NOTCH2 intracellular domain, which impedes the nuclear translocation of N2ICD." (PMID 25985737, 2015). "Here we demonstrate that NOTCH2 signalling is activated in HCC tumour tissues and liver CSCs, which is required for the maintenance of liver CSC self-renewal." (PMID 25985737, 2015). "Taken together, the NOTCH2 activation levels in tumour tissues are consistent with clinical severity and prognosis of HCC patients." (PMID 25985737, 2015). "Of note, bortezomib reversed tumor-induced downregulation of Notch receptors, Notch1 and Notch2, as well as increased the levels of cleaved Notch intracellular domain (NICD) and downstream targets Hes1 and Hey1 in tumor-draining CD8+T-cells." (PMID 26431276, 2015). "NOTCH2 knockdown dramatically reduced sphere formation, as well as attenuated xenograft tumour growth and tumour-initiating capacity." (PMID 25985737, 2015). "NOTCH1 and NOTCH2 protein expression in pretherapeutic tumor biopsies and response to neoadjuvant chemotherapy." (PMID 25954607, 2015). "One of the most interesting results of our study was the finding of higher expression of cytoplasmic NOTCH1 and of cytoplasmic and nuclear NOTCH2 in early tumor stages (pT1 + pT2), compared to advanced stages (pT3 + pT4)." (PMID 25954607, 2015). "And the strong positivity of Ki67 suggested a higher proliferation rate in NOTCH2 mutant DLBCLs compared to the paired non-tumor tissues." (PMID 25314575, 2014). "After Notch2-shRNA cells were transplanted into nude mice, tumor growth was significantly suppressed, the number of tumors decreased and survival time increased." (PMID 25323114, 2014). "On day 50 after inoculation, tumor weight in the Notch2-shRNA group was significantly lower than that in the negative-shRNA group (0.55±0.10 vs. 1.23±0.52 g; P<0.01)." (PMID 25323114, 2014). "Specifically, mRNA expression of NOTCH1 and NOTCH2 was elevated in tumor samples compared to normal bone (p < 0.05, q < 0.05)." (PMID 23816051, 2013). "To clarify this issue we analysed NOTCH2 protein expression by immunohistochemistry and included tumours from patients treated by surgery alone." (PMID 22970250, 2012). "Based on the cytoplasmic staining, our results confirm an increase in NOTCH2 expression at the protein level in the post-therapeutic tumours and they demonstrate that the observed differences are likely to be restricted to patients treated by chemotherapy." (PMID 22970250, 2012). "We thus separately designed a pair of primers that coordinate with the first intron of PTGFRN and the exon region of NOTCH2 to confirm this fusion in normal, adjacent non-tumor and cancer tissue by RT-PCR." (PMID 22905095, 2012). "NOTCH2 expression has been shown to be a prognostic predictor and is related to the tumor differentiation status in CRC." (PMID 22905095, 2012). "To evaluate the differences in gene expression between the paired pre- and post-therapeutic tumours on the protein level, we performed immunohistochemistry and focused on NOTCH2." (PMID 22970250, 2012). "Consistent with previous studies, Notch1 is present throughout all skin layers including the tumor-prone basal layer of the skin, whereas Notch2 is expressed exclusively in suprabasal keratinocytes." (PMID 21042537, 2010). "We also found that Msi1 increased NOTCH2 levels thus suggesting a potential role of Msi1 in contributing to tumor growth." (PMID 18826648, 2008).
tumor (continued). "Notably, the S100A2+ tumor cell subset also drives the progression from tumor precursors to PDAC by activating Notch2 signaling." (PMID 40092486, 2025). "In this study, we detected increased expression of Notch2 in 42% of tumor tissue." (PMID 41027955, 2025). "Notch1 and Notch2 were undetectable, whereas Notch4 was noted in limited number of tumor cells." (PMID 39548190, 2025). "NOTCH2 has a dual role, acting as an oncogene and tumor suppressor in different contexts." (PMID 40149537, 2025). "Among those, the Notch signaling pathway was found to be upregulated in preneoplastic lesions as well as in invasive tumors of the pancreas in both mice and humans, and targeting Notch2/Notch3 inhibited patient-derived xenograft tumor growth and decreased frequency of tumor-initiating cells." (PMID 39548190, 2025). "Notch-1 regulates proliferation, invasion, and chemoresistance; Notch-2 is involved in tumor transformation initiation; Notch-3 regulates proliferation, cell migration, and chemoresistance; Notch-4 controls epithelial-mesenchymal transition and therapy resistance." (PMID 41200177, 2025). "We further explored the potential influence of NOTCH2 on tumor immune evasion." (PMID 41200204, 2025). "In CRC, Notch1 and Notch2 have opposite roles in determination of the tumor biological behavior; Notch1 and Notch2 are independent adverse prognostic predictors, with a synergistic effect of positive Notch1 and negative Notch2 co-expression on predicting poor overall survival." (PMID 41294868, 2025). "Upregulation of NOTCH2 expression may promote tumor cell migration and invasion, while high expression of NOTCH3 may be positively correlated with tumor cell proliferation and volume." (PMID 39925808, 2025). "Overall, these findings suggest that NOTCH2 may facilitate immune evasion by fostering an immunosuppressive tumor microenvironment, ultimately contributing to tumor progression and therapeutic resistance." (PMID 41200204, 2025). "Several studies indicate that Notch2 signaling fosters tumor progression." (PMID 39766289, 2024). "Thus, we evaluated the expression of Notch1 and Notch2 to further explore the molecular mechanism by which the 3D microenvironment in the MC-B hydrogels regulates tumor aggressiveness in PC." (PMID 39057404, 2024). "However, Notch1 and Notch2 can delay tumor development and inhibit their growth once BRAF-induced tumors are initiated in Pten-null mice." (PMID 36672468, 2023). "Notch2 mediates the tumor-promoting effect of LINC01977 in HCC." (PMID 37198207, 2023). "However, in Pten-null background, the loss of either Notch1 or Notch2 appeared to accelerate BRAFV600E-induced tumor development, suggesting a tumor suppressor role for Notch1 and Notch2 in BRAFV600E/Pten-null driven melanomagenesis." (PMID 36672468, 2023). "Moreover, NOTCH1 and NOTCH2 expression was significantly reduced in cases with residual tumours (R1) (p = 0.03 and p = 0.02, respectively)." (PMID 36982928, 2023). "Human EGFR, Notch1, Notch2, and Notch3 mRNA were all expressed in tumours." (PMID 37441599, 2023).
tumor (continued). "In CRC pathogenesis, Notch2 overexpression may activate the GATA3/IL-4 pathway, which subsequently promotes the polarization of the tumor-associated macrophages toward an M2 phenotype and then enhances EMT." (PMID 36982677, 2023). "By extension, silencing NOTCH2 also decreased H69 tumor growth." (PMID 35612556, 2022). "In addition, targeting MUC1-C with a MUC1sgRNA, which suppressed MYC and NOTCH2 in vitro, resulted in complete inhibition of tumor growth." (PMID 35612556, 2022). "Based on this background, we hypothesised that N-Cadherin could play a role in BrCa dormancy and HSC-like stemness, cooperating with the Notch2 pathway in the process of dormancy and subsequent new tumour initiation ability." (PMID 35267624, 2022). "Overall, we can conclude that N-Cadherin could play a role in the induction and maintenance of tumour cell dormancy, in cooperation with Notch2." (PMID 35267624, 2022). "In particular, Notch2 expression was high in well-differentiated tumors and reduced in breast tumors with poor differentiation, while Notch1 may possess tumor-promoting functions." (PMID 35682974, 2022). "Furthermore, there were two genes (FBXW7, RET) mutated exclusively in tumours and eight (BLM, GJB2, NOTCH2, NOTCH3, NTRK1, POLE, SOS1, TSC2) solely in metastases." (PMID 34572946, 2021). "Importantly, miR-195-5p has been reported to play an essential role in regulating NOTCH2-mediated tumor cell EMT, thereby affecting IL-4-related M2-like TAM polarization in CRC." (PMID 34277412, 2021). "However, NOTCH2 was also reported to function as a tumor suppressor by inhibiting the PI3K/AKT pathway in MKN45 cells." (PMID 33452458, 2021). "Additionally, with less evidence, they also supposed a tumor-suppressive role for NOTCH2 and NOTCH3." (PMID 34205690, 2021). "The expression of ADAM10, Notch1, Notch2, Notch3, Notch4, Hey1, vimentin and N‐cadherin at the transcript level was significantly upregulated, whereas transcripts of E‐cadherin significantly decreased in tumour tissues versus in normal liver tissues of HCC." (PMID 33955149, 2021). "Of relevance, tumor microenvironment may determine an additional support in maintaining the expression of Notch2 and Mcl-1, especially at the lymph node level." (PMID 35070982, 2021). "However, inactivation of the Notch2 pathway in CD8+ cytotoxic T cells has also been reported to impair tumor immune response." (PMID 34205690, 2021). "Notch2 could promote tumor proliferation through regulating the levels of MYC (r = 0.8, P < 0.001) and MKI67 (r = 0.89, P < 0.001)." (PMID 33425722, 2020). "Blockade of NO synthase could restore the level of Notch1 and Notch2 in T cells as well as eliminate the MDSC-mediated immune suppression to re-establish anti-tumor responses." (PMID 33585446, 2020). "In addition, Met-1 tumor cells from obese mice expressed significantly higher expression of CSC-associated genes Sox2 and Notch Receptor 2 (Notch2), as well as Notch ligand Dll1 and downstream regulator Dtx2." (PMID 32098183, 2020). "Furthermore, endothelial Jagged-1 exerted an angiocrine function by activating Notch 2/HEY-1 in tumour cells promoting proliferation, survival and EMT." (PMID 32575680, 2020). "Thus, we evaluated the expressions of Notch-1 and Notch-2 to further explore the molecular mechanism by which the 3D microenvironment in MC-B hydrogels regulates tumor aggressiveness in OC." (PMID 33003514, 2020). "Here we show that the inhibition of NOTCH2 signaling by gliotoxin is associated with the recovery of a potentially non-canonical tumor suppressing NOTCH3 activity in CLL cells." (PMID 32570839, 2020).